CD74 (CD74 molecule)
Diseases named in the same sentence as CD74 in open-access papers (continued):
Sharing a sentence is not in itself a finding about the gene and the disease.
ciliopathy (1 paper, 2011). A genetic disorder of the cellular cilia or the cilia anchoring structures, the basal bodies, or of ciliary function. "In our model of ciliopathy-associated neurodegeneration, we identified CD74 and other components of the immunity system, expressed in microglia, as mediators of secondary vasoregression." (PMID 21379381, 2011).
Cognitive impairment (1 paper, 2025). Abnormal cognition is characterized by deficits in thinking, reasoning, or remembering. "Interestingly, MIF, a high-affinity ligand of CD74, has been reported to contribute to cognitive impairment in individuals with AD dementia in several studies." (PMID 41282231, 2025). "Delving into the possible role of CD74high microglia, one of the high-affinity ligands of CD74 is macrophage migration inhibitory factor (MIF), a pro-inflammatory cytokine that has been reported to contribute to cognitive impairment in individuals with AD dementia in several studies." (PMID 41282231, 2025).
colorectal adenoma (1 paper, 2022). An adenoma that arises from the colon or rectum. "An increased expression of CD74 in human colorectal adenomas was found to be related to an ascending grade of epithelial cell dysplasia, corresponding to the CIN stage in our study." (PMID 35208514, 2022).
congenital cataracts (1 paper, 2023). "We identified 18 HUB genes, among which four core genes, C1qa, C1qb, C1qc, and Cd74, were closely related to congenital cataracts induced by Crim1 mutation." (PMID 36586009, 2023). "In conclusion, through comprehensive biological analysis of the GSE62561 gene expression profile, a total of 750 DEGs were identified, of which C1qa, C1qb, C1qc, and Cd74 may be related to the occurrence and development of congenital cataracts caused by Crim1 mutations." (PMID 36586009, 2023).
dementia (1 paper, 2009). Loss of intellectual abilities interfering with an individual's social and occupational functions. "CD74- 33/35kD as well as total CD74 (data not shown) showed a tendency to increase in patients with severe dementia in both age categories." (PMID 19865478, 2009).
diarrhoea (1 paper, 2022). "Other DEGs that were down-regulated in the high-diarrhoea group include Ovar-DRB1, DQA, TREM2, TFF3, ITLN2, CD74, CCL5, and CCR3." (PMID 35140270, 2022).
endometrioid carcinoma (1 paper, 2025). "B7-H4, TROP2, and CD74 expression levels are significantly higher in endometrioid carcinoma than in serous carcinoma." (PMID 40046734, 2025). "In addition, target genes such as CD74, MSLN, NaPi2b and VEGF are more highly expressed in serous than in mucinous, clear and endometrioid carcinomas." (PMID 40046734, 2025). "In addition, the expression levels of target genes CD74, MSLN, NaPi2b, and VEGF are higher in serous carcinoma than in mucinous, clear cell and endometrioid carcinoma." (PMID 40046734, 2025).
endotoxemia (1 paper, 2024). "Plat+ capillaries are involved in the innate immune response through their interaction with neutrophils via ICAM-1 adhesion during endotoxemia, while Cd74+ capillaries epxressed high level of MHC proteins play a role in adaptive immune response through their interaction with T cells." (PMID 38348045, 2024).
enthesitis (1 paper, 2018). Inflammation at the site of insertion of ligaments, tendons, and other fibrous structures into bone. "In regression analysis within the population of patients with axSpA, sacroiliitis on MRI and heel enthesitis were both significantly associated with elevated anti-CD74 IgA odds ration (OR) = 2.50, p = 0.005 and (OR) = 2.56, p = 0.002, respectively)." (PMID 29490705, 2018).
focal segmental glomerulosclerosis (1 paper, 2024). A renal disorder characterized by sclerotic lesions in the glomeruli. "The data obtained from the Nephroseq database (nephroseq.org) revealed that CD74 expression was negatively correlated with eGFR in patients with IgA nephropathy, focal segmental glomerulosclerosis and other types of CKD." (PMID 38904010, 2024).
Graves disease (1 paper, 2020). Graves' disease is an autoimmune disorder that leads to overactivity of the thyroid gland (hyperthyroidism).It is caused by an abnormal immune system response that causes the thyroid gland to produce too much thyroid hormones. "The present study aims to investigate whether single-nucleotide polymorphisms (SNPs) in the MIF and CD74 are risk factors for developing Graves ophthalmopathy (GO) in patients with Graves disease (GD)." (PMID 32744317, 2020).
Headache (1 paper, 2025). Cephalgia, or pain sensed in various parts of the head, not confined to the area of distribution of any nerve. "Genetically, CD302 was associated with headache (P = 2.60 × 10−5), RARRES2 was associated with neck or shoulder pain (P = 3.94 × 10−4), TNFRSF1B was associated with back pain (P = 7.96 × 10−5), and CD74 was associated with hip pain (P = 3.21 × 10−4)." (PMID 40048323, 2025).
hematoma (1 paper, 2025). A hematoma is a collection of blood from a vascular structure into an extravascular space. "Syk potentially mediates Th2-polarized cytokine secretion (Il-6/Il-10), Cd36 enhances hematoma resolution via Il-10/Stat3 signalling and Cd74 synergizes with MIF to amplify inflammatory cascades." (PMID 40623122, 2025).
hepatitis C infection (1 paper, 2011). "Since full function of major histocompatibility complex needs both the invariant chain and variant chain, the PPIs among DQA1, DQB1 and CD74 may participate in the induction of hepatitis C and the development and progression from hepatitis C to HCC." (PMID 21526182, 2011). "The progression-related sub-network deregulated in hepatitis C infection stage was constructed with four nodes (HLA-DQA1, HLA-DQB1, HLA-DPA1 and CD74) and interactions among them." (PMID 21526182, 2011).
Herpes simplex infection (1 paper, 2022). "The KEGG pathway analysis highlighted that a large number of genes that were up-regulated after infection with V2 were the same as those upregulated in response to Herpes simplex infection (genes Myd88, Irf7, H2-Q7, Casp8, Tlr3, Daxx, C3, H2-Aa, Oas2, Oas3, H2-T22, H2-T23 and Cd74)." (PMID 35458422, 2022).
hyperglycaemia (1 paper, 2015). "As a ligand of MIF, CD74 protein and mRNA level was significantly up-regulated after STZ-induced hyperglycaemia, as detected by the immunohistochemistry, western blot and RT-PCR analysis." (PMID 25661015, 2015).
hyperthyroidism (1 paper, 2020). Overactivity of the thyroid gland resulting in overproduction of thyroid hormone and increased metabolic rate. "After PPI network construction, the top five hub genes associated with hypothyroidism were extracted, including ALB, MAPK1, SPP1, PPARG, and MIF, whereas those associated with hyperthyroidism were ALB, FCGR2B, CD44, LCN2, and CD74." (PMID 32500465, 2020). "The top five hub genes associated with hypothyroidism are ALB, MAPK1, SPP1, PPARG, and MIF, whereas those associated with hyperthyroidism are ALB, FCGR2B, CD44, LCN2, and CD74." (PMID 32500465, 2020).
inflammatory breast carcinoma (1 paper, 2023). An advanced, invasive breast adenocarcinoma characterized by the presence of distinct changes in the overlying skin. "The case of a CD74-ROS1 fusion in a 64-year-old inflammatory breast cancer patient (IBC) was found through NGS as a combination of CD74 exon 7 and ROS1 exon 34, which may have contributed to rapid disease progression as they died 18 months after tumor discovery." (PMID 37958963, 2023).
injury (1 paper, 2023). Damage inflicted on the body as the direct or indirect result of an external force, with or without disruption of structural continuity. "The combination of MIF and CD74 could also inhibit cell apoptosis, promote cell proliferation and alveolar epithelial cell repair, and at the same time play a role in reducing lung inflammation and acute lung injury." (PMID 37853311, 2023).
kidney (1 paper, 2023). "In the mouse UIRI kidney models, we verified that CD74 was significantly upregulated in AKI and CKD." (PMID 37511374, 2023).
leiomyosarcoma (1 paper, 2025). An uncommon, aggressive malignant smooth muscle neoplasm, usually occurring in post-menopausal women. "The MIF-CD74 and CXCR4-MIF/CD74 showed higher co-expression levels in undifferentiated pleomorphic sarcoma than in leiomyosarcoma." (PMID 40831537, 2025). "Spatial transcriptomic data revealed that MIF-CD74 and CXCR4-MIF/CD74 showed a higher positive correlation in undifferentiated pleomorphic sarcoma than leiomyosarcoma." (PMID 40831537, 2025). "Spatial transcriptomic data showed that co-expression levels of MIF-CD74 and CXCR4-MIF/CD74 were positively correlated in undifferentiated pleomorphic sarcoma, whereas the correlation was low in leiomyosarcoma." (PMID 40831537, 2025).
lepromatous leprosy (1 paper, 2018). A chronic communicable infection which is a principal or polar form of leprosy. "Ranking of lepromatous leprosy (LL) patients and healthy skin (HSk) according to their score of CD74 staining." (PMID 29487601, 2018).
leprosy (1 paper, 2018). Leprosy is a chronic infectious disease affecting primarily the skin and peripheral nervous system. "However, the expression of CD74 is significantly increased in the skin lesions of LL patients, although its participation in the physiopathology leprosy remains unclear." (PMID 29487601, 2018). "Further description of MIF and CD74, as well as the possibly involved signaling pathways, namely, PI3K, MAPK could yield valuable insight into leprosy immunopathology." (PMID 29487601, 2018). "Since MIF expression is not different between LL skin and HSk, we measured CD74 expression to determinate if it is involved in leprosy lesions." (PMID 29487601, 2018). "Given that 80% of new cases of leprosy Mexico are multibacillary cases, our observations of MIF and CD74 are limited to LL patients without treatment." (PMID 29487601, 2018).
listeria infection (1 paper, 2022). "In contrast, monocytes from the listeria infection model expressed M1-related transcription factors (e.g., Irf2, Mndal, Ifi204) and showed higher expression of CD38, CD74, and CD86, as well as higher ROS production." (PMID 36010615, 2022).
lupus erythematosus (1 paper, 2024). An autoimmune, connective tissue chronic inflammatory disorder affecting the skin, joints, kidneys, lungs, heart, and the peripheral blood cells. "Interestingly, CD74 protein was found in subsets of fibroblasts in prurigo nodularis, a chronic skin condition characterized by very itchy, firm lumps, and in a subset of antigen-presenting fibroblasts in lupus erythematosus, a chronic disease that causes inflammation in connective tissues." (PMID 39056788, 2024).
malaria (1 paper, 2022). Malaria is a serious and sometimes fatal disease caused by a parasite that commonly infects a certain type of mosquito which feeds on humans. "In a murine model of vaccination to prevent malaria, the use of a modified version of CD74 increased antibody responses against P. falciparum and the suppression of MIF-CD74 signaling also protected mice against severe malaria by P. berghei ANKA." (PMID 35646724, 2022).
malignant glioma (1 paper, 2023). A grade III or grade IV glioma arising from the central nervous system. "By performing differential expression analysis on our malignant glioma samples, we identified four DEGs, CD74, HES1, CALD1, and HEBP2, significantly upregulated in the AQP4 high expression group." (PMID 36599974, 2023).
memory impairment (1 paper, 2023). "Given the increase in Map+Cd74+ DAOs in the AD mouse brain, we next tested whether inhibition of Erk1/2 signaling attenuates DAO activation, which may alleviate memory impairments in AD mouse models." (PMID 36781874, 2023).
myocardial ischemia (1 paper, 2018). A disorder of cardiac function caused by insufficient blood flow to the muscle tissue of the heart. "Also, CXCR4 can form receptor complexes with CD7430,61, and MIF/CD74 signaling has important cardioprotective activities in myocardial ischemia/reperfusion injury." (PMID 29581527, 2018).
nephritis (1 paper, 2025). Inflammation of renal tissue. "Results showed that CD74 and MIF were up-regulated in glomerulus of anti-Thy1 nephritis on day 7 and decreased by AZD8797." (PMID 40458609, 2025).
nonalcoholic fatty liver disease (1 paper, 2020). "In the liver, CD74-MIF signaling plays a protective role in nonalcoholic fatty liver disease (NAFLD) by enhancing AMPK." (PMID 32655566, 2020).
ocular hypertension (1 paper, 2024). Abnormally high intraocular pressure. "We identified early and dynamic changes in the microglia functional phenotype, reactivity, and induction of a unique CD74 microglia population in the distal optic nerve as key features of ocular hypertension-induced neurodegeneration." (PMID 39568070, 2024).
osteoporosis (1 paper, 2025). A condition of reduced bone mass, with decreased cortical thickness and a decrease in the number and size of the trabeculae of cancellous bone (but normal chemical composition), resulting in increased fracture incidence. "Notably, two critical signaling pathways, MIF‐(CD74+CXCR4) and LGALS9‐CD45, were identified as potential key regulators driving the progression of osteoporosis." (PMID 41404455, 2025).
pancreatitis (1 paper, 2025). Inflammation of the pancreas. "Whereas for the DAFs in pancreatitis tissue, our results align with the prior findings of a median of ~20% CD74+ cells (+/−SEM 13%)." (PMID 40523922, 2025).
Pneumocystis infection (1 paper, 2010). "Among the genes that were affected by dexamethasone and further affected by Pneumocystis infection, Mgst1 and Hspa1b genes were down-regulated, while Cd14, Irf8, Il1b, Cxcl13, Cxcr4, Fn1, Irf1, Cd74, S100a9, and Spp1 genes were up-regulated in all four groups." (PMID 20377877, 2010).
polycystic kidney disease (1 paper, 2015). A usually autosomal dominant and less frequently autosomal recessive genetic disorder characterized by the presence of numerous cysts in the kidneys leading to end-stage renal failure. "Thus, like MIF, CD74 may protect from experimental kidney interstitial fibrosis but promotes glomerular injury, while MIF (and potentially CD74) also promotes polycystic kidney disease." (PMID 26441987, 2015).
primary Sjogren’s syndrome (1 paper, 2024). "Furthermore, scRNA-seq analysis of peripheral immune cells in patients with primary Sjogren’s syndrome highlighted not only enhanced CD74-COPA interactions between monocytes and naive B cells, but also CD74-amyloid beta precursor protein (APP) interactions between monocytes and memory B cells." (PMID 39493449, 2024).
progeria (1 paper, 2023). "Consistently, we found a significant increase in Mbp+ and Cd74+ DAOs in the hippocampus of premature progeria (6-month-old) and 13-month-old mice, whereas the number of NeuroD1-positive post-mitotic neurons decreased in the hippocampus of 13-month-old mice." (PMID 36781874, 2023).
prostate tumor (1 paper, 2005). "If MIF-CD74 interaction is needed for MIF to affect prostate tumor growth then CD74 should be localized within the prostate." (PMID 16000172, 2005).
prostatic adenocarcinoma (1 paper, 2005). "Additional aims were to examine MIF expression, as well as the location of MIF's receptor, CD74, in human prostatic adenocarcinoma compared to matched benign prostate." (PMID 16000172, 2005).
Pseudomonas infection (1 paper, 2024). Infections with bacteria of the genus pseudomonas. "However, Cd74, an adaptive immune marker, is known to be decreased in Pseudomonas infection." (PMID 38792580, 2024).
psoriasis (1 paper, 2024). An autoimmune condition characterized by red, well-delineated plaques with silvery scales that are usually on the extensor surfaces and scalp. "We identified APP pathway-related ligand receptor proteins, including APP and CD74 (CD74 Antigen), with upregulated protein expression in pathological tissue sections of psoriatic skin (Psoriasis/Normal skin Ratio in CD74 protein: 1.202; Psoriasis/Normal skin Ratio in MIF protein: 1.239)." (PMID 38289616, 2024).
renal carcinoma (1 paper, 2025). A carcinoma arising from the epithelium of the renal parenchyma or the renal pelvis. "They discovered two subgroups: VEGFA + SPP1 +, which is significantly overexpressed in renal cancer and linked to tumor angiogenesis and growth, and HLA-DR + CD74 +, which is present in renal cancer and contributes to antitumor immunity by activating T cells." (PMID 41035074, 2025).
retinal dystrophies (1 paper, 2025). "Elevated CD74 levels in response to inflammation have been detected in retinal dystrophies but were restricted to activated microglia located near vessels that undergo vasoregression." (PMID 40251274, 2025).
sacroiliitis (1 paper, 2018). "Furthermore, anti-CD74 IgA was associated with sacroiliitis on magnetic resonance imaging (MRI) (OR) = 2.50, p = 0.005) and heel enthesitis (OR) = 2.56, p = 0.002)." (PMID 29490705, 2018). "First, the percentage of patients with non-radiographic axSpA who were positive for anti-CD74 IgG antibodies was lower (43.9%), suggesting that either the antibodies develop over time or that they are associated with radiographic sacroiliitis rather than with the diagnosis of axSpA per se." (PMID 29490705, 2018). "Patients with axSpA with radiographic sacroiliitis more often had anti-CD74 IgA antibodies than patients with axSpA without radiographic sacroiliitis (66.7% vs. 46.4%, p = 0.031)." (PMID 29490705, 2018).
sarcoidosis (1 paper, 2025). Sarcoidosis is a multisystemic disorder of unknown cause characterized by the formation of immune granulomas in involved organs. "While sarcoidosis fibroblasts also upregulated CXCL9 and CD74, they exhibited only modest increases in CCL5 and FN1." (PMID 39989459, 2025). "Reanalysis of a sarcoidosis scRNA-seq dataset revealed that, similar to NL and NXG, sarcoidosis lesional fibroblasts expressed high levels of MHC (e.g., HLA-B and HLA-DRA), CD74, PLOD2, STAT1, TNC, PRSS23, PSMB9, and CXCL9." (PMID 39989459, 2025). "Thus, while CD74- and CXCL9-expressing inflammatory fibroblasts are present in sarcoidosis, their phenotype does not perfectly match the CCL5hi fibroblasts seen in NL and NXG fibroblasts." (PMID 39989459, 2025).
Shock (1 paper, 2013). The state in which profound and widespread reduction of effective tissue perfusion leads first to reversible, and then if prolonged, to irreversible cellular injury. "We observed that among these five MHC class II-related genes, the invariant chain (CD74) mRNA was the best predictor of 28-day mortality after septic shock." (PMID 24321376, 2013). "In this respect, we observed for the first time that, among MHC class II genes, a decreased CD74 mRNA level presented with the best predictive value in regard to 28-day mortality after septic shock." (PMID 24321376, 2013).
silicosis (1 paper, 2025). Silicosis is a respiratory disease caused by breathing in (inhaling) silica dust. "It was found that CD68 and APP interacted with CD74 on CD31 in the silicosis group and the Tet group, but not in the normal group, the H2 group and the H2 + Tet group." (PMID 41561355, 2025).
spondylitis (1 paper, 2025). The inflammation of a vertebra. "Median CRP (IQR) values were higher (3.9 (1.0; 8.0) vs. 2.4 (1.0; 7.2)) and the impairment of spinal mobility according to the median BASMI (Bath Ankylosing Spondylitis Metrology Index, IQR) more severe in patients with elevated anti-CD74 Abs (1.3 (0.0, 3.0) vs. 1.0 (0.0, 2.0))." (PMID 40063233, 2025).
thoracic tumors (1 paper, 2018). "In order to assess the effect of the MIF/CD74 pathway in the development of MPM, we derived a new human MPM cell line expressing MIF, CD74, and CD44 and able to generate orthotopic intra-thoracic tumors." (PMID 29949929, 2018).